UCA1 (urothelial cancer associated 1)
Diseases named in the same sentence as UCA1 in open-access papers (continued):
Sharing a sentence is not in itself a finding about the gene and the disease.
lymph node metastasis (continued). "Meanwhile, the pooled data of eligible studies also indicated that high UCA1 expression was significant correlated with poor grade cancer (pooled OR = 2.74, 95% CI 2.04–3.70, p < 0.001, I2 = 49.5%, pH = 0.1) and positive lymph node metastasis (pooled OR = 2.43, 95% CI 1.72–3.41, p < 0.001)." (PMID 28423704, 2017). "Additionally, the pooled odds ratios (ORs) showed that increased UCA1 was also related to positive lymph node metastasis (OR = 2.98, 95% CI: 2.06–4.30), distant metastasis (OR = 3.14, 95% CI: 1.77–5.58) and poor clinical stage (OR = 2.76, 95% CI: 2.08–3.68)." (PMID 27517147, 2016). "But gender, age, tumor size, and lymph node metastasis had no relation with UCA1 and miR-182-5p expression level." (PMID 31996265, 2020). "The combination of HOTTIP, PVT1, and UCA1 is identified to be a clinical predictive panel to differentiate CRC patients with lymph node metastasis from CRC patients with non-metastatic lymph nodes and healthy people." (PMID 31480503, 2019). "The expression level of UCA1 in TSCC cells with lymph node metastasis (LNM) is significantly higher than those without LNM." (PMID 29416703, 2018). "Meanwhile, multivariable Cox regression analysis displayed that lymph node metastasis (present vs. absent), expression of UCA1 (high vs. low) and expression of ENSG00000218510 (high vs. low) were independent predictors of PDAC patients’ overall survival after pancreatectomy." (PMID 27628540, 2016).
esophageal squamous cell carcinoma (22 papers, 2014 to 2026). Esophageal squamous cell carcinoma (ESCC) is a type of esophageal carcinoma (EC) that can affect any part of the esophagus, but is usually located in the upper or middle third. "Prior studies have demonstrated that UCA1 suppresses c‐Myc expression as a cancer suppressor in esophageal squamous cell carcinoma (ESCC)." (PMID 40567251, 2025). "The predicted top five lncRNAs are MALAT1, MEG3, BCYRN1, UCA1, and LSINCT5, among which MALAT1 and MEG3 are found to be associated with esophageal squamous-cell carcinoma in lncRNADisease in 2017." (PMID 35186029, 2022). "For example, it has been reported that a higher lncRNA UCA1 expression was found in esophageal squamous cell carcinoma tissues compared with normal tissues, while down-regulation of UCA1 decreases esophageal squamous cell ability of migration and proliferation." (PMID 30200918, 2018). "A four-lncRNA panel (POU3F3, UCA1, PEG10, and ESCCAL-1) within exosomes has been used for diagnosing esophageal squamous cell carcinoma (ESCC)." (PMID 40703556, 2025). "Through literature search, UCA1 and LSICT5 are found to be related to esophageal squamous-cell carcinoma." (PMID 35186029, 2022). "In esophageal squamous cell carcinoma (ESCC), it demonstrated that UCA1 could inhibited cell proliferation, migration, invasion, and cell cycle progression of EC109 cells, and UCA1 could involve in ESCC development by regulating the Wnt signaling pathway." (PMID 28380443, 2017).
acute myeloid leukemia (19 papers, 2015 to 2024). Acute myeloid leukemia (AML) is a group of neoplasms arising from precursor cells committed to the myeloid cell-line differentiation. "In acute myeloid leukemia (AML) cells, the lncRNA UCA1 induced autophagy, which was associated with cell proliferation." (PMID 33050642, 2020). "In a study of patients with acute myeloid leukemia, potential interaction network was identified involving long noncoding RNAs (lncRNA) UCA1/hsa-miR-16-5p/COL4A5." (PMID 39049724, 2024). "Through the UCA1/miR-125a/HK2 axis, UCA1 knockdown decreased chemoresistance in acute myeloid leukaemia by reducing glycolysis." (PMID 36639695, 2023). "In the previous study, we demonstrated that lncRNA UCA1 modulates cell proliferation and apoptosis by regulating miR-296-3p/Myc axis in acute myeloid leukemia." (PMID 35178087, 2022). "The reduction in miR-204 has been related to UCA1 expression in acute myeloid leukemia (AML) cultured cells and in patients." (PMID 34200849, 2021). "In acute myeloid leukemia, lncRNA UCA1 promotes autophagy by targeting miR-96-5p." (PMID 33869042, 2021). "LncRNA UCA1 promotes acute myeloid leukemia (AML) progression by affecting the stability of METTL14 and upregulating the expression of CXCR4 and cytochrome P450 family 1 subfamily B member 1 (CYP1B1)." (PMID 38351139, 2024). "There have identified a number of lncRNAs association with several subtypes of leukemia, such as MEG3, IRAIN, and UCA1 related to acute myeloid leukemia (AML) and ANRIL, LUNAR1, in ALL." (PMID 34101758, 2021). "Another example is UCA1, one of the most common lncRNAs, which is highly expressed in acute myeloid leukemia (AML) and enhances cell proliferation by suppressing the expression of cell cycle regulator p27kip1." (PMID 30466456, 2018). "Moreover, MEG3, UCA1, and H19 are upregulated in acute myeloid leukemia." (PMID 26448935, 2015). "UCA1 stabilizes METTL14 allowing the writer to deposit m6A marks on target mRNAs, such as CYP1B1 and CXCR4, leading to acute myeloid leukemia (AML) development." (PMID 39280246, 2024). "UCA1 is upregulated in acute myeloid leukemia (AML) following adriamycin (ADR)-based chemotherapy." (PMID 33652661, 2021). "In acute myeloid leukemia (AML), UCA1 can be used as an endogenous sponge to compete with miR-126, which in turn suppresses activation of the PI3K/AKT signaling pathway by inhibiting the expression of RAS-related C3 botulinus toxin substrate 1 (RAC1)." (PMID 33777227, 2021). "In acute myeloid leukemia (AML), extracellular lncRNAs LINC00265, LINC00467, UCA1, and SNHG1 are promising biomarkers for disease diagnosis and treatment monitoring." (PMID 39886670, 2024).
esophageal cancer (19 papers, 2017 to 2024). A primary or metastatic malignant neoplasm involving the esophagus. "Urothelial Cancer Associated 1 (UCA1) acted as ceRNA directly combining miR-498, a tumor suppressor, inhibiting its function in esophageal cancer cells." (PMID 38948025, 2024). "In esophageal cancer cells, UCA1 uses ceRNA to adsorb miR-498, causing changes in downstream ZEB2 expression and exerting cancer-promoting effects." (PMID 35241975, 2022). "Some studies have been carried out to investigate the influence of the expression of LncRNA human urothelial carcinoma associated 1 (UCA1) on prognosis and clinical significance in patients with esophageal cancer, but the results are contradictory and uncertain." (PMID 33879677, 2021). "The study provides updated evidence to evaluate whether the expression of LncRNA UCA1 is in association with poor prognosis in patients with esophageal carcinoma." (PMID 33879677, 2021). "Previous studies have also found that overexpression of UCA1 played anticancer roles in esophageal cancer cells through inhibiting cell proliferation, invasion and migration, colony formation, and cell cycle progression." (PMID 37081402, 2023). "In oesophageal cancer, UCA1 can promote tumour glucose metabolism via the UCA1/miR-203/HK2 axis, contributing to cancer cell proliferation and metastasis." (PMID 36639695, 2023). "In this study, systematic evaluation and meta-analysis were conducted to further evaluate the correlation between the expression of LncRNA UCA1 and the prognosis of patients with esophageal carcinoma." (PMID 33879677, 2021). "Based on bioinformatics analysis, this study enhanced the understanding of the mechanism and related pathways of LncRNA UCA1 in esophageal carcinoma." (PMID 33879677, 2021). "Odd ratio and its 95% confidence intervals were applied to evaluate the relationship between LncRNA UCA1 and clinicopathological characteristics of esophageal carcinoma patients." (PMID 33879677, 2021). "Subsequently, GO, KEGG, and PPI network analysis were conducted based on the overlapping target genes of LncRNA UCA1 to explore the possible molecular mechanism in esophageal carcinoma." (PMID 33879677, 2021). "There were only two studies reporting the relationship between UCA1 and clinicopathological features of esophageal cancer." (PMID 28380443, 2017). "However, UCA1 acted as a tumor suppressor gene in the esophageal cancer, the expression level is lower in the cancer tissues than that in the adjacent tissues." (PMID 37564930, 2023). "However, UCA1 exerts anti-migratory and -invasive roles in esophageal cancer, showing that the function of UCA1 is dissimilar, depending on cancer types." (PMID 35055115, 2022). "In conclusion, our meta-analysis could provide latest evidence for the correlation between LncRNA UCA1 and the prognosis of patients suffering from esophageal carcinoma." (PMID 33879677, 2021). "In addition, bioinformatics analysis was conducted to investigate the mechanism and related pathways of LncRNA UCA1 in esophageal carcinoma." (PMID 33879677, 2021). "LncRNA UCA1 decreases in patients suffering from esophageal carcinoma." (PMID 33879677, 2021). "lncRNA UCA1 was overexpressed in esophageal cancer cells and was prone to predict poor prognosis." (PMID 28388588, 2017). "Urothelial cancer associated 1 (UCA1) has been shown to increase the activation of HK2 by inhibiting miR203 and to regulate glucose metabolism by increasing glucose uptake and lactic acid production, promoting the proliferation and metastasis of esophageal cancer (Liu H.-E." (PMID 35004688, 2021). "Therefore, LncRNA UCA1 may become a potential biomarker of prognosis in patients with esophageal carcinoma." (PMID 33879677, 2021). "Dysregulated lncRNAs, such as UCA1, HOTAIR, and TUG1, have been proposed as prognostic biomarkers for esophageal cancer." (PMID 35619131, 2022).
esophageal cancer (continued). "lncRNAs (AFAP1-AS1, UCA1, HOTAIR) were found to be dysregulated in cisplatin-resistant esophageal cancer cells compared with the corresponding parent cells." (PMID 28388588, 2017). "This demonstrates that UCA1, POU3F3, CCAT2, HOTAIR, and uc002yug. could be important prognostic factors among patients with esophageal cancer." (PMID 35241975, 2022). "Publication bias and sensitivity analysis were not applicable in analyzing the relationship between UCA1 and clinicopathological features of esophageal cancer, because of the limited number of studies without between-studies heterogeneity." (PMID 28380443, 2017).
non-small cell lung carcinoma (19 papers, 2015 to 2024). A group of at least three distinct histological types of lung cancer, including non-small cell squamous cell carcinoma, adenocarcinoma, and large cell carcinoma. "LncRNA urothelial carcinoma associated 1 (UCA1) was reported to be upregulated in non-small cell lung cancer (NSCLC) tissues and contributed to NSCLC progression." (PMID 35540445, 2018). "Additionally, insights from the GSE231938 dataset revealed a positive association between GLS1 and IGF2BP3 in non-small cell lung cancer, prompting further exploration into the interplay among GLS1, IGF2BP3 and UCA1." (PMID 38760723, 2024). "In addition, the overexpression of lncRNA UCA1 in urothelial carcinoma is associated with chemotherapy resistance, and silencing lncRNA UCA1 can inhibit the migration and invasion of non-small cell lung cancer cells and reverse the drug resistance of cancer cells." (PMID 37180267, 2023).
osteosarcoma (19 papers, 2017 to 2024). A usually aggressive malignant bone-forming mesenchymal neoplasm, predominantly affecting adolescents and young adults. "UCA1 mediates EMT and activates the PI3K/Akt/mTOR pathway via the UCA1/miR-582/CREB1 axis to promote osteosarcoma metastasis." (PMID 35610231, 2022). "Among those cancers, lncRNAs are more widely researched in osteosarcoma, including lncRNA-21A, UCA1, MEG3, HULC, and MIR31HG." (PMID 36057712, 2022). "In osteosarcoma, UCA1 knockdown inhibits miR-301a expression and induces the silencing of C-X-C chemokine receptor type 4 (CXCR4), thus decreasing cell proliferation and metastasis." (PMID 33777227, 2021). "In osteosarcoma, inhibition of UCA1 downregulates miR-301a expression and decreases CXCR4 expression, thus suppressing cell proliferation and metastasis." (PMID 33777227, 2021). "These included lncRNAs TUG1, HOTAIR and UCA1 which were slightly elevated in lung metastatic osteosarcomas." (PMID 32728178, 2020). "Furthermore, amplified miR-301a expression can prevent the suppressive action of knockdown of UCA1 in cells from osteosarcomas, a process that can be reversed by inhibiting CXCR4." (PMID 39015175, 2024). "LncRNA UCA1 promoted osteosarcoma metastasis by activating mTOR signaling pathways." (PMID 36807122, 2023). "Similarly, macrophage-derived chemokine CCL18 upregulates UCA1 expression through transcription factor EP300 in osteosarcoma." (PMID 33777227, 2021). "Notably, lncRNA GAS8-AS1 inhibits migration and invasion of osteosarcoma cells by downregulating UCA1 expression." (PMID 33777227, 2021). "Dysregulation of lncRNA MEG3 could act as a potential predictor of the progression and poor prognosis of osteosarcoma, and overexpression of lncRNAs UCA1 and TUG1 are essential in the poor prognosis of osteosarcoma." (PMID 31850493, 2020). "Recent study showed that UCA1 is able to regulate CXCR4 in osteosarcoma cells." (PMID 30940776, 2019). "UCA1 can inhibit PTEN and promote p-AKT expression to induce the proliferation of osteosarcoma cells." (PMID 33777227, 2021). "In laryngeal squamous cell carcinoma, NSCLC, osteosarcoma and HCC, serum UCA1 levels of patients are higher than that of the healthy control population." (PMID 33777227, 2021). "For example, nine lncRNAs (91H, FGFR3-AS1, BCAR4, TUG1, UCA1, HIF2PUT, HOTTIP, HULC, and MALAT-1) are up-regulated in osteosarcoma, which is considered oncogenic for osteosarcoma." (PMID 31850493, 2020). "Notably, it has been demonstrated that UCA1 increases CREB1 expression by acting as a competitive endogenous RNA (ceRNA) of miR-582, thus promoting EMT via the CREB1-mediated mTOR pathway, which results in osteosarcoma metastasis." (PMID 33777227, 2021).
liver cancer (18 papers, 2015 to 2024). An epithelial or non-epithelial malignant neoplasm that arises from the liver. "For instance, circulating LINC00152, HULC and UCA1 have been associated with gastric and liver cancer, two organs that are in close proximity within the upper abdomen and which both originate from the foregut of the embryonic endoderm." (PMID 35729321, 2022). "Other examples of LTR-promoted oncogenic lncRNAs include HULC for Highly Upregulated in Liver Cancer, UCA1 (urothelial cancer associated 1) and BANCR (BRAF-regulated lncRNA 1)." (PMID 27980689, 2016). "In liver cancer, lncRNA UCA1 contributes to chemotherapy resistance and malignant transformation of hepatocyte-stem cells." (PMID 29967761, 2018). "Furthermore, lncRNA UCA1 also induces the expression of lncRNA HULC (highly upregulated in liver cancer) in liver cancer and lncRNA HULC in turn stimulates the activity of the Wnt-β-catenin pathway." (PMID 29967761, 2018). "For the liver cancer, it found that upregulated UCA1 could promote cell growth and tumorigenesis through the signaling of HBx-UCA1/EZH2-p27Kip1 axis in hepatocarcinogenesis." (PMID 28380443, 2017). "However, a previous report showed that the elevation of UCA1 in liver cancer (2 in 14 cases) was not as high as in our present study." (PMID 25760077, 2015).
colon cancer (17 papers, 2014 to 2024). "We find that LINC00114 and UCA1 are upregulated in colon cancer which to be associated with the early tumor stage." (PMID 33832120, 2021). "LINC00114 and UCA1 are confirmed to be associated with the early stages of colon cancer." (PMID 33832120, 2021). "Among the top 10 lncRNAs predicted by VGAELDA, UCA1 facilitates the progression of colon cancer through upregulating miRNA miR-28-5p and HOXB3." (PMID 33745450, 2021). "Ten lncRNAs, 8 miRNAs, and 6 mRNAs were involved in the ceRNA network, in which LINC00114 and UCA1 were highly expressed in colon cancer." (PMID 33832120, 2021). "The expression of LINC00114 is higher in stage I and UCA1 is lower, indicating that they can be used for early colon cancer diagnosis." (PMID 33832120, 2021). "Experimental results show that the control network composed of UCA1 and other RNAs is a potential factor in the treatment of colon cancer." (PMID 34193046, 2021). "Long noncoding RNA (lncRNA) UCA1 promoted colon cancer progression through sequestering miR-28-5p to elevate the HOXB3 level." (PMID 34013042, 2021). "Eventually we find that LINC00114 and UCA1 are upregulated in colon cancer tissues compared to normal tissues." (PMID 33832120, 2021). "LINC00114 and UCA1 are both highly expressed in colon cancer tissues compared to normal tissues in the TCGA database." (PMID 33832120, 2021). "From our literature review, we found that several lncRNAs among the ceRNA network, such as lncRNAs UCA1, GAS5, MALAT1, and PVT1, are associated with oncogenesis and the development of colon cancer." (PMID 30984308, 2019). "LncRNA Plasma UCA1 can be used as a potential biomarker for inchoate diagnosis and monitoring of colon cancer." (PMID 31572428, 2019). "Overexpression of lncRNA UCA1 is also a reason for chemoresistance against 5-fluorouracil treatment in colon cancer." (PMID 29967761, 2018). "What is more, as the lncRNA can be secreted by cancer cells or released into the circulation from dead cancer cells, it has been reported that UCA1 level in plasma significantly decreased 14 days after surgery of colon cancer." (PMID 28074092, 2016). "For example, the association between colon cancer and MALAT1, HOTAIR, UCA1, KCNQ10T1, and CRNDE (ranked 2nd, 4th, 6th, 7th, 9th in the prediction results, respectively) were validated by lncRNADisease database or MNDR database." (PMID 26577439, 2015). "Two novel lncRNAs (LINC00114 and UCA1) in colon cancer were identified by bioinformatics analysis." (PMID 33832120, 2021). "Few studies have focused on the function of UCA1 in colon cancer." (PMID 33832120, 2021). "In colon cancer (CRC), UCA1 plays a key role in CRC tumor progression by packaging into exosome, and UCA1 sequesters mir-143 via a sponge mechanism." (PMID 35359390, 2022). "The intersection of CRC vs. N and CRC vs. Ad comparisons defines lncRNAs characteristic of malignancy in colonic tumors, where significant downregulation of LINC01752 and overexpression of UCA1 and PCAT1 were found." (PMID 31694571, 2019). "We also predict two novel pathways, UCA1/miR-107/PCKS5 and UCA1/miR-129-5p/SEMA6A in colon cancer." (PMID 33832120, 2021). "In addition, LINC00114/miR-107/PCSK5, UCA1/miR-107/PCKS5, and UCA1/miR-129-5p/SEMA6A axes may play an important role in colon cancer carcinogenesis and require further research." (PMID 33832120, 2021).